HMGB1 (high mobility group box 1)
Diseases named in the same sentence as HMGB1 in open-access papers (continued):
Sharing a sentence is not in itself a finding about the gene and the disease.
infection (continued). "High-mobility group box 1 (HMGB1) was initially described as a nuclear factor enhancing transcription and was associated with infection, injury, and inflammation." (PMID 35341159, 2022). "During infection or cell injury, HMGB1 undergoes post-translational modifications, including acetylation, methylation and phosphorylation, causing its translocation from the nucleus to cytoplasm before being released into the extracellular environment." (PMID 35058496, 2022). "OVs can induce ICD with various features, such as causing ER stress, HMGB1 and ATP release, and elevated surface expression of CRT during infection." (PMID 36755812, 2022). "In this study, we found that HMGB1 was released from the nucleus to the extracellular in macrophages upon infection with MG." (PMID 36139393, 2022). "The infection was found to induce HMGB1 nuclear-to-cytoplasmic translocation, resulting in a > 99% increase in the cytosolic HMGB1 expression at 72-h post-infection (h.p.i)." (PMID 35058496, 2022). "HMGB1-RAGE/TLR4-axis has been attributed to a central role in influenza virus-induced infection models." (PMID 35633962, 2022). "The infection with E. coli O55 increased HMGB1 levels in the amniotic fluid compared to the saline-treated amnions." (PMID 34439812, 2021). "In contrast to the relation of IAI and increased HMGB1 levels, it seems that infection-induced intra-amniotic inflammations are less frequent than sterile inflammation." (PMID 34439812, 2021). "Although the exact active secretion mechanism of HMGB1 remains elusive, a recent study has revealed that C5a engagement with its receptor C5aR2 in macrophages upon infection induces upregulation of HMGB1 expression and release through intracellular signaling." (PMID 33807604, 2021). "The infection downregulated HMGB1 mRNA expression in the amniotic membrane, changed the distribution of HMGB1 protein in the amniotic membrane, and increased its level in amniotic fluid." (PMID 34439812, 2021). "In summary, we reported that HMGB1 plays an important role in BoHV-1 productive infection in MDBK cells." (PMID 34008469, 2021). "High Mobility Group Box 1 (HMGB1) functions as a proinflammatory mediator in response to infection and stress." (PMID 34258068, 2021). "NDV upon infection induce the secretion of high mobility group box 1 (HMGB1) that promotes the production of inflammatory cytokine storm." (PMID 33406695, 2021). "Future studies should determine the isoform proportions and if the HMGB1 is passively or actively released after the burn with infection with P. aeruginosa M2." (PMID 34152806, 2021). "In mammals, signals that can induce HMGB1 secretion include pathogen infection, damage, and other stresses such as hypoxia, drug treatment, and lethal irradiation." (PMID 34671276, 2021). "This means that HMGB1 was capable of disseminating inflammatory response in the endothelium during infection or injury." (PMID 33505216, 2021). "Following infection, these cells respond to PAMPs and become activated to release pro-inflammatory cytokines and DAMPs including high-mobility group box 1 (HMGB1), extracellular cold-inducible RNA-binding protein (eCIRP), and histones." (PMID 33708213, 2021). "HMGB1 is released into the extracellular space during infection, cell damage, or inflammation, and extracellular HMGB1 induces inflammatory cytokine expression in systemic tissues, functioning as damage-associated molecular patterns (DAMPs)." (PMID 34083649, 2021). "In fact, HMGB1 is secreted by endotoxin‐activated macrophages, and secretion increases 20–72 h after infection." (PMID 33140586, 2021). "In contrast, in the presence of infection, serum HMGB1 levels peaked at 250 ng/ml (i.e., >10-fold increase) after the burn with infection and remained elevated until death." (PMID 34152806, 2021).
infection (continued). "Here, we showed that BoHV-1 productive infection in MDBK cells at later stage significantly increases HMGB1 mRNA expression and the protein release, but decreases the steady-state protein levels." (PMID 34008469, 2021). "Once released, extracellular HMGB1 can bind many endogenous proteins, thereby modulating divergent innate immune responses to lethal infections." (PMID 34571869, 2021). "Of note, the released HMGB1 during the infection of various viruses, such as respiratory syncytial virus (RSV), hepatitis C virus (HCV), Herpes simplex virus type 2 (HSV-2), and HSV-1, has been convinced to exacerbate severity of the inflammatory disease." (PMID 34008469, 2021). "Knockdown studies in this cell line have shown that the intracellular protein high mobility group box 1 (HMGB1) acts as an inductor of autophagy in epithelial cells by preventing STAT3 activation in infection assays with S. Typhimurium." (PMID 34276584, 2021). "As expected in B6 cells, S. Tm or LPS+ATP treatment led to significant HMGB1 release into the supernatant by one-hour post-infection, and by 4 hours post-exposure to Yptb or staurosporine (Sts)." (PMID 34648590, 2021). "Western blot analyses revealed that lenti-shHMGB1 infection remarkably decreased HMGB1 expression which significantly inhibits proliferation and facilitate apoptosis of AML cells as compared with the lenti-control (lenti-ctrl) infection." (PMID 33128580, 2021). "A similar effect was observed in response to low dose LPS as a model of subclinical infection with increased uric acid, HMGB1 and HSP70 release." (PMID 33790316, 2021). "Apart from infection, a previous study by Menon on placental senescence demonstrates that HMGB1 activates DAMP which upregulates expression of prolabor genes in normal parturition." (PMID 34258068, 2021). "In mice subjected to burn alone or burn with infection, increased HMGB1 concentrations preceded the elevation in serum cytokines." (PMID 34152806, 2021). "We next assessed the levels of serum HMGB1 in the context of burn injury and P. aeruginosa M2 infection." (PMID 34152806, 2021). "Our results confirmed significantly higher levels of HMGB1 in the culture medium of R. africae-infected cells, thus corroborating more pyroptotic events in this infection condition." (PMID 34935429, 2021). "Increased HMGB1 levels play a role in the lung injury produced by infections with Staphylococcus aureus and carbapenem-resistant Klebsiella pneumoniae." (PMID 34271850, 2021). "The increase in survival in the P5779-treated group shows that circulating HMGB1 contributes significantly to the inflammation generated from the burn plus infection and suggests that HMGB1 should be studied further as a potential therapeutic target." (PMID 34152806, 2021). "For instance, infection or cellular stress has been shown to increase the cytoplasmic accumulation of HMGB1, which is then passively released into the extracellular space or actively secreted via secretory lysosomes." (PMID 32587593, 2020). "In response to infection and injury, HMGB1 can be actively secreted from activated immune cells or passively released from damaged or necrotic cells and transferred outside the cell." (PMID 32660524, 2020). "HMGB1 is a nuclear protein released from immune cells or injured nonimmune cells and a critical mediator of various inflammatory responses to injury, infection, and inflammation." (PMID 33005688, 2020). "In the lung, butyrate suppresses HMGB1 induction to infection, suggesting that it will act to prevent the HMGB1 inhibition of RvD1 and the RvD1 resolution of activated neutrophils." (PMID 32867244, 2020). "Overall, our results suggest GTS-21 attenuates the release and accumulation of extracellular HMGB1 by attenuating oxidative stress/infection-induced activation of NF-κB and its down-stream pre-inflammatory responses." (PMID 33126860, 2020).
infection (continued). "HMGB1 can undergo several extensive PTMs that increase its cytoplasmic accumulation and extracellular secretion during infection or cell stress, including acetylation, phosphorylation, ADP-ribosylation, methylation, glycosylation, and oxidation." (PMID 32587593, 2020). "Together, these studies suggest that following RSV infection, HMGB1 contributed to the development of the type 2 response during the course of infection." (PMID 32397226, 2020). "HMGB1 can be released by DCs, macrophages, and NK cells in response to inflammatory stimuli, including infection, and is also released from necrotic and dead cells." (PMID 32397226, 2020). "In this study, mice were infected with RSV and were subsequently treated with an HMGB1 antibody on days 14 to 20 post-infection." (PMID 32397226, 2020). "High-mobility group box 1 (HMGB1) is a ubiquitously expressed protein that can be released from cells during infection or sterile inflammation." (PMID 32917873, 2020). "HMGB1 expression in the human bronchial epithelial cell line 16HBE was increased following infection with RSV compared to un-infected cells." (PMID 32397226, 2020). "More specifically, HMGB1 has been demonstrated to be involved in immune responses to infection, injury, and inflammation in mammals." (PMID 32070432, 2020). "HMGB1 is a very important proinflammatory cytokine and can stimulate the immune system to protect against infections." (PMID 33187536, 2020). "As a mediator of sterile inflammation and infection, HMGB1 has an important role in injury-elicited inflammatory diseases including trauma, but evidence in elderly hip fracture patients is lacking." (PMID 32466360, 2020). "If these HMGB1-activated host defense mechanisms are appropriately controlled and downregulated, they play an important protective role in the eradication of infection, as well as in promoting tissue repair." (PMID 32664328, 2020). "Bearing that in mind, should the increase in HMGB1 gene expression stem from the infection alone, it would be pronounced in our patients, as well." (PMID 32796569, 2020). "Leaning on in vitro research, the increase in HMGB1 expression in the course of different infections was fast." (PMID 32796569, 2020). "The pharmacological inhibition of HMGB1 release and activity by drugs (e.g., chloroquine and glycyrrhizin) has shown significant protective effects on lethal infection in mice." (PMID 32442210, 2020). "Extracellular HMGB1 is a late inflammatory mediator released after infection with West Nile virus, atypical pneumonia virus, porcine reproductive and respiratory syndrome virus, grass carp reovirus." (PMID 32070432, 2020). "When HMGB1 is released from necrotic cells following infections or tissue damage, it will elicit a TLR4-dependent cytokine storm (largely TNF, IL-6, IL-1, and IL-10) in immune cells (e.g., monocytes, macrophages, neutrophils, and lymphocytes)." (PMID 33313438, 2020). "Under normal conditions, HMGB1 binds to the minor groove of DNA and bends it to facilitate gene transcription, but under stressed conditions such as injury or infection, HMGB1 is released and promotes inflammatory responses." (PMID 31011483, 2019). "Lastly, intestinal TLR4 mRNA upregulation and HMGB1 protein levels were increased in both TLR4 and HMGB1 proteins in the pig ileal tissue 120 hrs after the infection with Clostridium perfringens type C." (PMID 31847111, 2019). "The higher intestinal HMGB1 levels in the S. Typhimurium-infected groups suggest that secretion was in response to the infection." (PMID 31847111, 2019). "The cytokine HMGB1, which is produced in response to injury, infection, and inflammatory stimuli, is secreted by activated macrophages, mature dendritic cells, and natural killer cells." (PMID 31151297, 2019). "Infection with P. aeruginosa resulted in increased levels of HMGB-1 that peaked at POD 7 in DPT burn wounds." (PMID 31998665, 2019).
infection (continued). "HMGB1 is actively secreted to the extracellular milieu by components of the immune system, platelets and endothelium following infection and exposure to inflammatory mediators." (PMID 31379812, 2019). "Similar to the effect on HMGB1 release, an Ad WT infection inhibited the release of mature caspase-1 and IL-1ß subunits into the media." (PMID 31849970, 2019). "In the present study, during the different time points of post-AHPND infection, several genes functioning as PRRs (C-type lectin, galectin) and DAMPs (galectin, HMGB1) were identified to be upregulated." (PMID 31372182, 2019). "HMGB1 is shown to be involved in several pathological developments such as inflammation, injury, infection, and a variety of diseases." (PMID 31336567, 2019). "NDV/FMW infection of both A375 and C8161 cell lines at 24 or 48 h resulted in an increase of extracellular ATP and HMGB1, respectively, as determined by ELISA assay." (PMID 31192135, 2019). "High mobility group box 1 (HMGB1) is a major family member of injury-related molecules (DAMPs) involving in infection, injury and inflammation." (PMID 30755598, 2019). "During the time of tissue injury, inflammation and infection, HMGB1, a DNA binding protein will be released from the nucleus and activates inflammatory and immune responses through binding to a group of receptors including RAGE and members of the TLR family." (PMID 31818258, 2019). "Like other members of the pro-inflammatory cytokine family, biologically active HMGB1 can be expressed on the plasma membrane or released by activated inflammatory cells to accumulate in vivo during infection." (PMID 30157804, 2018). "Using shRNA targeting HMGB1, we successfully depleted HMGB1 from 3T6 cells in both total cell lysates and in cell supernatants following HSV1716gfp infection." (PMID 29543735, 2018). "In summary, this study demonstrates a novel mechanism by which NETs through the release of HMGB1 induce Mφ pyroptosis, which in turn plays an important role in directing the progress of inflammation following infection." (PMID 29789550, 2018). "A wealth of evidence shows that HMGB1 is involved in the course of infections by viruses, including DNA and RNA viruses." (PMID 29316268, 2018). "Although both virus doses induced similar levels of HMGB1 at 4 days p.i., infection with 1 × 105 TCID50 resulted in lower HMGB1 levels at later times, indicating a dose dependency." (PMID 29535197, 2018). "In our study mRNA expression of HMGB1 was down regulated after LPS stimulation and up regulated after infection with E. coli, in spleen homogenate in more extent than in brain, which implicates a different course of inflammatory response." (PMID 29755322, 2018). "For patients with severe infection, it has been proposed that HMGB1 release predominantly occurs locally, at the site of infection." (PMID 30194360, 2018). "Excessive extracellular HMGB1 contributes to the pathogenesis of infection- and injury-elicited inflammatory diseases." (PMID 29447234, 2018). "HSV1716gfp infection decreases cell proliferation, which is partially restored by HMGB1 inhibition and significant at several time points." (PMID 29543735, 2018). "Further, although both NIH-3T3 and 3T6 Swiss albino cells secrete HMGB1 following HSV1716gfp infection, only conditioned media from 3T6 Swiss albino is cytotoxic." (PMID 29543735, 2018). "In response to infections and injuries, HMGB1 is secreted from activated immune cells or passively released from injured cells." (PMID 29447234, 2018). "Extracellular HMGB1 acts as a multifunctional cytokine that contributes to infection, injury, inflammation, and immune responses by binding to specific cell-surface receptors." (PMID 30258438, 2018). "Regardless, the P5 peptide dose-dependently attenuated the LPS-induced release of HMGB1, a critically important mediator of infection- and injury-elicited inflammatory diseases." (PMID 29317708, 2018).
infection (continued). "Inoculation with the live attenuated vaccine FluMist resulted in HMGB1 levels that were significantly lower than those with infection with live influenza viruses." (PMID 29535197, 2018). "Peak HMGB1 concentrations were significantly higher in patients who went on to develop an infection (p = 0.04)." (PMID 29675023, 2018). "CRS-HIPEC is associated with profound DAMP release and immune suppression, and plasma HMGB1 levels are related with the occurrence of postoperative infections in these patients." (PMID 29675023, 2018). "Third, a larger cohort is required to confirm the observed relationship between HMGB1 and postoperative infections, and to determine its predictive value." (PMID 29675023, 2018). "In this way, HMGB1 acts as a classical DAMP to alert the host to infection or damage that has compromised the nuclear membrane." (PMID 28067797, 2017). "Further peritoneal lavage fluid results showed that HMGB1 was secreted at 6 h after infection and continuous secretion was detected in the following periods, similarly to the in vitro assay using ANA1 cells." (PMID 28484433, 2017). "HMGB1 is a ubiquitous nuclear and cytosolic protein and released by damaged or necrotic cells during sterile inflammation and infection." (PMID 29207644, 2017). "HMGB1 is usually detected at the later stages of infection when it is translocated out of the nucleus and further secreted out of the cell." (PMID 28216632, 2017). "For this, infected mice were treated with ceftriaxone 21 h after infection, while 3 h later, mice received anti-HMGB1 antibodies." (PMID 29096648, 2017). "When cell damage occurs, HMGB1 is translocated to the cytoplasm and released by the cell to act as a multifunctional cytokine with roles in infection, organ dysfunction, inflammation, and immune responses." (PMID 29283384, 2017). "In BALB/c mice infected by Mycobacterium tuberculosis strain H37Rv, the maximal HMGB1 concentration in bronchoalveolar lavage fluid (BALF) was at day 1 after infection, and HMGB1 is mainly from bronchial epithelium and macrophages." (PMID 28039939, 2017). "During cell activation, infection, injury or death, HMGB1 translocates from the nucleus into the cytoplasm and eventually out of the cell." (PMID 28216632, 2017). "Upon infection or injury, inflammasomes were shown to mediate extracellular release of HMGB1 from stimulated immune cells triggering inflammation." (PMID 28979266, 2017). "Meanwhile, blocking HMGB1 during early infection period relieves the disease, but blocking HMGB1 activity during late infection worsens the disease." (PMID 28039939, 2017). "HMGB1, a DNA binding protein, usually exists in the nucleus and can be translocated out of nucleus during stress, infection or physical injury." (PMID 28216632, 2017). "From day 7 to 21 after infection, the oxidized HMGB1 is predominant, while the reduced form is detected during late stage." (PMID 28039939, 2017). "Similar to the primary infection, the proportion of AECs with cytoplasmic HMGB1 and levels of HMGB1 in BALF were significantly elevated in infected compared to vehicle-inoculated IPS-1−/− mice, and were significantly greater than in WT mice." (PMID 28539639, 2017). "During infection or injury, activated immune cells and damaged cells release HMGB1 into the extracellular space, where it functions as a proinflammatory mediator and contributes to the pathogenesis of inflammatory diseases." (PMID 28592850, 2017). "RAGE deficient mice were treated daily for four days from the time of re-infection with anti-HMGB1 or an isotype-matched control." (PMID 28099113, 2017). "We also observed oscillations in levels of cytokine mediators TNF-α and HMGB-1 as the infection was resolved." (PMID 27556404, 2016). "Patients with the severe PUUV infection indicated the highest HMGB1 level among HFRS and CCHF patients, although infection with DOBV and CCHFV usually cause more severe hemorrhagic manifestations than PUUV." (PMID 27348219, 2016).